CAT (catalase)
Diseases named in the same sentence as CAT in open-access papers (continued):
Sharing a sentence is not in itself a finding about the gene and the disease.
infection (continued). "TSP and three redox enzymatic (SOD, CAT and POD) activities showed significant interaction between genotypes and post infection time (P < 0.05)." (PMID 33259527, 2020). "Collectively, the levels of SOD, CAT, POD, APX, and PAL activities are the physiological characteristics to analyze and quantify the strawberry host resistance against pathogen infection." (PMID 31428350, 2019). "The results showed that both D39 infection and H2O2 stimulation up-regulated the expression of STING in A549 cells, and the induction of STING was reduced by 20% by catalase treatment, a 40% reduction was observed after infection with D39ΔspxB." (PMID 30984149, 2019). "IE treatment significantly reduced the infection-induced increase in NO and MDA levels and increased the level of GSH as well as the activity of catalase." (PMID 30838089, 2019). "From 12h to 72h post-infection, compared with the lean group, the contents of MDA and GSH, and the activities of GSH-Px, CAT and SOD significantly raised (p<0.05) in the lean-E." (PMID 31085802, 2019). "Our study showed that, after infection of Bemisia tabaci by L. lecanii, the activities of SOD, CAT, and POD initially increased but then decreased thereafter, and the maximum activities protective enzymes were observed on the 2nd day or 3rd day." (PMID 31576242, 2019). "In our present study, the content of oxidative product (MDA) and antioxidants (GSH) and activity of antioxidase (SOD, CAT, and GSH-Px) were increased in the infected groups at 12 h after infection." (PMID 30250258, 2018). "On the 28th day of infection and 23 days of treatment, the euthanasia occurred, and the heart preserved for histopathological, oxidative stress (SOD, catalase, TBARs, carbonylated proteins) and plasma (CCL2, CCL5, TNF, IL-10) analyses." (PMID 30365644, 2018). "As expected from the higher levels of lipoperoxidation, the liver extracts of P. berghei NK65 infected mice were characterized by a lower CAT activity and lower levels of total glutathione (GSH + GSSG) at both days post infection." (PMID 29316914, 2018). "On the contrary, P. chabaudi AS-infected mice showed CAT and SOD activity and GSH levels similar to control at both days post infection, whereas GR activity was higher at both time points." (PMID 29316914, 2018). "To summarize, the enzymatic response of B. tabaci to combined matrine and L. muscarium treatment displays a reduction in CarE, GSTs and CHI during the initial infection period, whereas SOD, POD and CAT activities decreased during the later infection period." (PMID 28425450, 2017). "CAT, POX and PO were expected to increase as a result of infection, while PPO was expected to decrease due to conversion to PO." (PMID 28572677, 2017). "For example, the expression levels of some DEGs enriched in “negative regulation of apoptosis” functional pathway were up-regulated after infection, but other DEGs’ expression levels were down-regulated (including FAIM, CAT and KRT18)." (PMID 29073164, 2017). "Different antioxidant enzymes such as superoxide dismutase (SOD), catalase (CAT), ascorbate peroxidase (APx) and guaiacol peroxidase (GPx) involved in ROS metabolism during pathogen infection." (PMID 29098503, 2017). "P. indica inoculated plants showed an increase in SOD, GR, CAT and GST activities which help plants to overcome infections and stresses." (PMID 29051515, 2017). "Infection with ST resulted in substantial reduction in the expression of SOD-1, SOD-2, catalase and GADD45A, perhaps to allow ROS levels to build-up to control the pathogen." (PMID 27599659, 2016). "The reduction of SOD-1, SOD-2, catalase and GADD45A was much more pronounced in the livers of FoxO3a−/− mice following infection with ST." (PMID 27599659, 2016). "In our study, when L. migratoria were treated with M. anisopliae alone, CAT, SOD and POD activities increased during the initial period of infection." (PMID 27328936, 2016).
infection (continued). "Alterations of T-SOD, MDA and CAT in the serum and major organs of HepG2- SCID mice after DV2 infection." (PMID 23383181, 2013). "It was previously established that the resistance of T. aestivum to the S. nodorum SnB isolate is determined by the intensive generation of ROS, mainly H2O2, due to the lack of an increase in CAT activity during the initial stage of infection." (PMID 39942917, 2025). "However, we found that the activities of CAT and SOD in D. sylvestrella larvae infected with strain Bb01 increased significantly from 6 to 48 h post-infection." (PMID 40559070, 2025). "Additionally, antioxidant and defense-related enzymes (SOD, CAT, APX, and LOX) exhibited increased activity during the early stages of infection but decreased activity at later stages." (PMID 40822715, 2025). "Notably, Pb-PR-1-11, Pb-PR-1-21, and Pb-PR-1-26 expression increased with infection duration, aligning with PPO and CAT activity trends." (PMID 40507885, 2025). "The treatment of plants with ABA slightly increased CAT activity in all the cultivars in the absence of infection." (PMID 39942917, 2025). "SOD, CAT, and POD activities increased by 27.5%, 75.8%, and 45.7%, respectively (p < 0.01), effectively scavenging reactive oxygen species (ROS) generated during pathogen infection." (PMID 41440698, 2025). "Antioxidant enzymes such as CAT and SOD were analyzed on the 8th day after infection." (PMID 41278479, 2025). "Antioxidant enzymes such as CAT and SOD were analyzed 9th day after infection." (PMID 41001420, 2025). "In further in vivo experiments, SlRP5 alleviated B. cinerea-induced membrane damage by reducing MDA and REC levels, while simultaneously enhancing the activities of antioxidant enzymes such as SOD, CAT, and POD, thereby mitigating the excess ROS generated by infection." (PMID 40034157, 2025). "The increase in SOD in this group was likely sufficient to neutralize reactive species, such as superoxide anions, generated by immune cells in response to infection; therefore, the activities of the GPx and CAT enzymes were not modified." (PMID 40332798, 2025). "Moreover, oxidative stress induced by crowding, poor water quality, and pathogen infection impairs the activity of key antioxidant enzymes-superoxide dismutase (SOD), catalase (CAT), and glutathione (GSH), thereby exacerbating tissue damage and mortality." (PMID 41300513, 2025). "During the early storage period (0–2 days), the activities of SOD, CAT, POD, and APX in the rno group were significantly higher than those in the ck group, suggesting that pathogen infection triggers the host's active ROS scavenging mechanism to delay oxidative damage." (PMID 40980280, 2025). "infection dampens NLRP3 activation by modulating mitochondrial ROS production, partly through upregulation of antioxidant enzymes such as superoxide dismutases (SOD1 and SOD2), catalase (CAT), and glutathione peroxidase (GPx)." (PMID 41404367, 2025). "In our study, SlRP5 pretreatment not only moderately increased the activities of SOD and CAT under nonpathogenic conditions but also further enhanced the activities of SOD, CAT, and POD after infection with B. cinerea, thereby strengthening the plant’s defense mechanisms." (PMID 40034157, 2025). "Additionally, 1–4 g/kg of TA improved the T-SOD, CAT, and GSH-Px activities during infection, while 2 g/kg of dietary TA enhanced the richness and diversity of the microbiota, for example, by increasing Actinobacteria but inhibiting Firmicutes." (PMID 39857447, 2025). "For instance, research on the resistance of leaves from four early-maturing pear varieties to black spot disease revealed that following pathogen infection, the activities of POD, SOD, and CAT significantly increased in the leaves of Cuiguan pear and Sucui No. 1 pear." (PMID 40507885, 2025).
infection (continued). "Additionally, CAT and GPX expression levels were markedly elevated in the oregano and sodium butyrate-supplemented groups after infection, with the highest expression observed at the 1% oregano + 1% sodium butyrate dose." (PMID 41188425, 2025). "Interestingly, the combined treatment (INO + AZA + MEF) maintained the highest CAT activity among inoculated plants, similar to the CONTROL treatment at an early stage of infection (3 dpi) and still relatively high at 9 dpi, before declining at 21 dpi." (PMID 41304631, 2025). "Upon FORL infection, treated plants exhibited strong upregulation of PR1, chitinase and β-1,3-glucanase genes mirrored by sustained increases in H2O2 and phenolic content and peroxidase, catalase, chitinase and β-1,3-glucanase activity." (PMID 41348951, 2025). "Moreover, at 24 h postinjection, the expression of CAT and SOD in response to the infection was still significantly higher than in the control group." (PMID 40276584, 2025). "The ROS generated during the infection triggers the release of antioxidants molecules, including SOD, GPx, catalase, albumin, ceruloplasmin, ferritin, ascorbic acid, α-tocopherol, β-carotene, reduced glutathione, uric acid, and bilirubin, all of which are included in the measurement of TAS." (PMID 39852665, 2025). "Immune enzymes (PO, CAT, POD) were initially activated but later inhibited, while detoxification enzymes (GSTs, CarE, AChE) were largely suppressed, weakening the insect’s defense against infection." (PMID 40870660, 2025). "Therefore, we conclude that during D. sylvestrella larvae infection by strain CGMCC3.2055, ROS are mainly regulated by SOD, CAT, and POD." (PMID 40559070, 2025). "Similarly, CAT and GSH levels also exhibited significant increases (**** p < 0.0001), while TAC showed a pronounced elevation under infection conditions." (PMID 41152306, 2025). "However, the CAT, SOD, and POD activities of transgenic Arabidopsis were significantly increased compared with those of WT plants 36 h after infection with B. cinerea." (PMID 39062632, 2024). "In our previous research, it was found that the overproduction of H2O2 was accompanied by an increase in CAT activity, with a simultaneous decrease in APX activity, in the initial stage of infection, as well as an increase in SOD activity, in the later stage of infection development." (PMID 38920663, 2024). "For instance, in the larvae of Holotrichia parallela, following joint infection of entomopathogenic nematode and Bacillus thuringiensis, there was an initial increase in GST and CAT activity during the early stage, followed by a decrease in activity in the later stage." (PMID 39628478, 2024). "Overall, the CAT activity and expression level of ScCAT in the four cultivars were decreased or not significantly changed under Xa infection alone or combined stress." (PMID 38592879, 2024). "However, until now, there has been no comprehensive study analyzing changes in the numerical abundances of peroxisomes and mitochondria and their respective main antioxidant enzymes, catalase and SOD2, after BoDV1 infection." (PMID 38339126, 2024). "Furthermore, another study reported a significant decrease in catalase (CAT) and glutathione (GSH) levels, along with an increase in malondialdehyde (MDA) levels, in the tissues and hemolymph of B. alexandrina following infection with S. mansoni." (PMID 38302641, 2024). "This phenomenon may be attributed to the escalating spore load in the late infection stage, leading to a prolonged intensification of V. ceranae stress in the host and consequently suppressing the activities of SOD, CAT, and GST." (PMID 39628478, 2024). "In addition, the activated antioxidant system, including SOD, CAT, POD, GR, and GPX, maintained a redox balance during the infection, which finally contributed to the promotion of A. alternata pathogenicity in kiwifruit." (PMID 39590720, 2024).
infection (continued). "Consistent with a central role for oxidative stress responses in cell-intrinsic responses to infection, key antioxidant enzymes (GSR, CAT, GPX1, and PRDX1) were downregulated by YFV-17D and select genes (SOD2, NFE2L2, and KEAP1) were upregulated by MnTBAP treatment." (PMID 39282299, 2024). "In this scenario, the CAT activity played the pivotal role in the elimination of H2O2 rather than the APX activity, which seemed to be higher at an advance stage of infection by B. maydis." (PMID 39795339, 2024). "After BoDV1 infection, a strong decrease in mitochondrial (2.1–6.5-fold), SOD2 (2.7–9.1-fold), and catalase (2.7–10.3-fold) abundances, but a slight increase in peroxisomes (1.3–1.6-fold), were detected in Wt and TNFR2ko mice, whereas no changes occurred in TNFR1ko mice." (PMID 38339126, 2024). "Infection with HPV virus that incorporates into the cellular genome results with higher ROS due to the expression of oncoproteins and the reduction of circulating antioxidants such as superoxide dismutase, catalase, glutathione peroxidase and GSH." (PMID 38125616, 2024). "Additionally, the activated antioxidant system, including SOD, CAT, POD, GR, and GPX, supported redox balance during the infection, which ultimately contributed to the promotion of A. alternata pathogenicity." (PMID 39452678, 2024). "In small doses ROS are useful as a defense against infection but in large amounts they become harmful; for this reason, there are antioxidant enzymes that degrade them such as superoxide dismutase (SOD), catalase (CAT), glutathione peroxidase (GSH-Px), and paraoxonase (PON)." (PMID 36670997, 2023). "In this study, the activities of CAT and POD in the early stage of infection showed an upward trend, whereas the contents of ROS and free radicals did not change significantly, indicating that the outbreak of ROS activated the antioxidant system response in plants." (PMID 38248924, 2023). "Furthermore, the activities of SOD, POD, CAT, and PAL were significantly increased in GmPR1L-overexpressing soybean plants after seven days of infection." (PMID 37107678, 2023). "For the VIDES extract, a 15 min application produced an 83% increase in CAT activity, whereas a 181% increase in GR activity compared to plants without infection was produced after a 30 min application." (PMID 37631184, 2023). "However, there was a significant decline in SOD, CAT, and GST enzyme activities at 48 h after infection, and during this time, the infected larvae began to die." (PMID 36835731, 2023). "Enzymatic analysis revealed altered ACP, ALP, catalase, and SOD enzyme activity in third instar larvae of S. frugiperda infected with M. majus, thus indicating that the entomopathogenic fungi alters the insect immune system to enable infection." (PMID 36937255, 2023). "Inoculated sugarcane plants modulated the reactive oxygen species (ROS) homoeostasis by enhancing respiratory burst oxidase homolog (ScRBOH) expression and superoxide dismutase (SOD) activity and by decreasing catalase (CAT) activity, especially after infection by X. albilineans XaCN51." (PMID 36589125, 2022). "The activities of five enzymatic antioxidant agents, including the superoxide dismutase (SOD), Catalase (CAT), Guaiacol peroxidase (GPX), Ascorbate peroxidase (APX), and Glutathione reductase (GR) were also investigated during infection with IPO323 and ΔAvrStb6#33." (PMID 36388590, 2022). "In L. vannamei, intramuscular injection of 0.1 μg (g shrimp)−1 fluorescent red polyethylene microspheres and experimental infection with Enterocytozoon hepatopenaei both resulted in a significantly increase in SOD activity and a significant decrease in CAT activity." (PMID 36189245, 2022).
infection (continued). "Since H2O2 accumulation was observed in the interaction, the activities of five enzymatic antioxidant agents (e.g. SOD, CAT, GPX, APX, and GR) were measured following infection by the employed strains to examine their potential role in the pathosystem, complying with the AvrStb6-Stb6 relationship." (PMID 36388590, 2022). "In summary, dietary MOS enhanced the antioxidant ability of juvenile M. amblycephala by inducing or maintaining the activities of SOD, CAT, and GST, which could assist in increasing the survival rate of M. amblycephala upon infection." (PMID 35784342, 2022). "Additionally, assays of enzymes involved in plant resistance to pathogen infection, such as POD, SOD, PPO, PAL and CAT, were also performed, and the activities of all these enzymes were significantly higher than in the control." (PMID 36008749, 2022). "infection at six dpi, suggested that bone marrow is not a CAT active site during Eimeria infection, but lower level of Eimeria infection can stimulate synthesis of enzymatic antioxidant in bone marrow." (PMID 35923236, 2022). "Resistant parasites also appear to be unaffected by H2O2 since neither this reactive species (even with the increase in RNS production) nor the presence of catalase were able to change the infection index." (PMID 35204161, 2022). "It was observed that the NDVI has a negative correlation with PAL activity, weight, and height before infection without B. c-A; and after infection had a positive correlation with CAT and SOD activity." (PMID 35406912, 2022). "The treatment of Aag2 with 0.25 μM DPI or 50 U/ml catalase did not impact cell infection by both strains at 4 h." (PMID 34485182, 2021). "“Gratiaviridae” phages might deploy catalase- and DPS-like enzymes during infection to enhance the tolerance of their strictly anaerobic Bacteroides hosts to oxidative damage." (PMID 33781338, 2021). "As for pregnancy, although it did not cause changes in the activity of SOD and MDA, it led to increased CAT activity as gestational trimesters advanced, regardless of the infection status." (PMID 34019550, 2021). "Comparing infection and non-infection (control group), according to the non-pregnancy factor, the CAT levels were higher in the infected patients (p = 0.0008)." (PMID 34019550, 2021). "Thus, in the current study, we investigated the role of different antioxidant enzymes (SOD, POD, CAT, and APX) in the defense mechanism of capsicum cultivars, enabling them to mitigate the infection damage on them." (PMID 33941790, 2021). "In addition, Ca2+ significantly increases the activity of the antioxidant enzymes like superoxide dismutase (SOD), catalase (CAT), peroxidase (POD), and polyphenol oxidase (PPO) to scavenge reactive oxygen species (ROS) after pathogen infection." (PMID 34281232, 2021). "The increase in CAT and SOD activities is consistent with previous studies, revealing that the most potent treatment led to strong activities of antioxidant enzymes, which ultimately tremendously declined at the lateral stage of infection." (PMID 33926109, 2021). "By fixing the infection, CAT activity was lower for pregnant women compared to non-pregnant at M0 (p = 0.01) and M1 (p = 0.004)." (PMID 34019550, 2021). "Furthermore, we examined the activities of four enzymes, SOD, CAT, POD, and PAL, as well as the MDA content in WT, empty vector, and transgenic lines after infection with pathogens." (PMID 34629466, 2021). "The fact that infection did not affect the levels of the peroxisomal matrix enzyme catalase indicates that the effect of the virus on peroxisomal proteins is highly specific." (PMID 32127461, 2020). "However, CAT activity was significantly higher in inulin- and LOS-treated leaves 24 h after infection with B. cinerea." (PMID 32882794, 2020). "Interestingly, GABA pre-treatment significantly primed the activities of CAT and GPX in response to B. cinerea infection, whereas BABA pre-treatment induced the activities already before infection." (PMID 33255543, 2020).